TFAM (transcription factor A, mitochondrial)
Diseases named in the same sentence as TFAM in open-access papers (continued):
Sharing a sentence is not in itself a finding about the gene and the disease.
Insulin resistance (18 papers, 2014 to 2026). Increased resistance towards insulin, that is, diminished effectiveness of insulin in reducing blood glucose levels. "Human studies provide evidence that the expression of the TFAM gene is regulated by DNA methylation of its promoter region, and this methylation has been associated with insulin resistance in adolescents." (PMID 37679776, 2023). "Supplementation with RA increases the expressions of the mitochondrial biogenesis genes like PGC-1α, SIRT1, and TFAM through activation of AMPK in the skeletal muscles of rats with insulin resistance as well as in L6 myotubes." (PMID 38903985, 2024). "For example, inhibition of mitochondrial respiration in adipocytes by knocking down mitochondrial transcription factor A (TFAM) or application of several mitochondrial respiration inhibitors induced insulin resistance and impaired adipokine secretion." (PMID 29124204, 2015). "Indeed, evidence from human studies indicates that TFAM gene transcription is regulated by DNA methylation of its promoter, and this correlates with the onset of insulin resistance in adolescents." (PMID 37679776, 2023). "It is noteworthy that hypermethylation of the promoter for genes such as PGC-1α, COX7A1, and TFAM may be involved in mitochondrial function and insulin resistance." (PMID 25436770, 2014). "In addition, a previous study indicated that mice with deletion of muscle-specific mitochondrial transcription factor A (TFAM), which controls the transcription of all mitochondrial encoded genes, did not develop insulin resistance." (PMID 36983072, 2023). "Additionally, factors such as Cox7A1 and TFAM may also lead to mitochondrial dysfunction in insulin resistance." (PMID 25436770, 2014). "Studies show that adipocyte-specific knockout of TFAM results in adipose inflammation, BAT whitening, severe lipodystrophy, insulin resistance, and decreased EE in obese mice." (PMID 41532014, 2026). "EA improves glycolipid metabolism and alleviates insulin resistance in T2DM rats, potentially via activation of the AMPK/PGC-1α/TFAM pathway." (PMID 41469741, 2025). "(silymarin) on factors involved in mitochondrial biogenesis (Pgc-1α, TFAM, SIRT), inflammation (NFκB), and antioxidant enzymes (SOD), which recovered glycemic and lipid homeostasis and reduced insulin resistance and hepatic steatosis in an obese mouse model." (PMID 35326098, 2022). "HFD induces insulin resistance and remarkably reduces expressions of transcriptional co-regulator of mitochondrial biogenesis (PGC-1α), mitochondrial transcription factor A (TFAM) and the mitochondrial OXPHOS complexes in the hippocampus." (PMID 33379163, 2020). "Additionally, different studies have proposed potential DNA methylation biomarkers in relation to plasma insulin levels, insulin secretion and insulin resistance such as those located in PPARGC1A, HTR2A, LY86, TFAM, GIPR, ADIPOQ, and IGFBP3 genes." (PMID 31208038, 2019).
lung carcinoma (17 papers, 2012 to 2025). "Loss of mitochondrial transcription factor A (TFAM) in a mouse model of K-ras driven lung cancer demonstrated reduced tumor growth." (PMID 31426364, 2019). "In support of this conclusion, disruption of mitochondrial function caused by loss of the mitochondrial transcription factor A (TFAM) gene reduced tumorigenesis in an oncogenic K-Ras-driven mouse model of lung cancer." (PMID 22917272, 2012). "In addition, loss of mitochondrial transcription factor A (TFAM), a transcription factor required for mtDNA replication, inhibited tumor formation in an in vivo mouse model of K-Ras-driven lung cancer." (PMID 25671107, 2014). "Furthermore, disruption of mitochondrial function due to deficiency of the mitochondrial transcription factor A (TFAM) gene could decrease tumorigenesis in an oncogenic Kras-driven mouse model of lung cancer." (PMID 40927188, 2025). "Here, SP2509 effectively restored the expression of genes such as CTSE and TFAM in the lung cancer of KMS mice, along with the restoration of H3K4me3." (PMID 40057469, 2025). "Beyond metabolic reprogramming, TFAM knockdown has also been shown to enhance migration and/or invasion in lung cancer cells, renal carcinoma cells, gastric cancer cells, head and neck cancer cells and hepatocellular cells." (PMID 41398603, 2025). "To understand the cause-and-effect link between the increase in mtDNA copy number and lung cancer development, we took advantage of well-characterized mouse models with different levels of mtDNA due to altered expression of TFAM." (PMID 39485842, 2024). "Xie reported that the down-regulation of TFAM inhibited lung cancer cell tumorigenesis, leading to increased apoptotic cell death." (PMID 30862036, 2019). "Consistent with a prior study, a negative association between tumor size and TFAM expression has been reported in lung cancer." (PMID 41398603, 2025). "In this context, TFAM expression and/or mtDNA content could possibly be used as prognostic markers for lung cancer or to stratify patients that undergo mitochondria-targeted therapies in the future." (PMID 39485842, 2024). "In lung cancer cell lines, we also observed that SP2509 restored the expression of CTSB, LC3B, and TFAM, which were suppressed by MEN1-KD." (PMID 40057469, 2025).
colon carcinoma (15 papers, 2014 to 2026). "No other significant correlation was identified between TFAM expression and other clinicopathological factors, including the association between TFAM expression and metastasis of colon cancer (p <0.05)." (PMID 27732955, 2016). "TFAM may be associated with the promotion of cancer cell growth and metastasis in bladder, esophageal, gastric, and colon cancers." (PMID 37627097, 2023). "TFAM is identified as a direct target of miRNA-590-3p; in bladder cancer, a downregulation of miRNA-590-3p expression correlates with a marked increase in TFAM expression, while in colon cancer, an elevation in miRNA-590-3p expression is associated with a significant decrement in TFAM expression." (PMID 38476236, 2024). "Knockdown of TFAM has been shown to significantly decrease mitochondrial respiration and increase glycolysis in colon cancer cells." (PMID 35955761, 2022). "TFAM is a requirement for normal replication and transcription of mtDNA; this is evidenced as reduced mtDNA content in colon carcinoma cell lines as well as in biopsies carrying truncating mutations in TFAM." (PMID 25243473, 2014). "Additionally, TFAM promotes the growth and metastasis of colon cancer in vitro and in vivo, while SIRT6 was inhibited." (PMID 41362737, 2026). "In terms of mechanism, overexpression of miRNA-590-3p might promote the growth of tumor cells by targeting TFAM in colon cancer." (PMID 28938537, 2017). "In conclusion, we found that Agr inhibited colon carcinoma progression by promoting oxidative stress and cell apoptosis by blocking the PGC-1α/NRF1/TFAM signaling pathway." (PMID 36591497, 2022). "In tissues from colon cancer patients, less CD3+CD8+ T cells and the higher expression of the mitochondrial biomarker TFAM were found." (PMID 35464857, 2022). "MiR-214-3p can inhibit the cell viability and development of colon cancer by inhibiting ADP-ribosylation factor-like protein 2 (ARL2) and mitochondrial transcription factor A (TFAM)." (PMID 33628646, 2021).
Alzheimer disease (14 papers, 2019 to 2025). A progressive, neurodegenerative disease characterized by loss of function and death of nerve cells in several areas of the brain leading to loss of cognitive function such as memory and language. "Meanwhile, several population-based studies have suggested that the single nucleotide polymorphism (SNP) of rs1937 on TFAM were associated with Alzheimer’s disease (AD)." (PMID 34979947, 2022). "Animal studies have also revealed a reduction in the levels of PGC-1α, Nrf1, Nrf2, and TFAM in the brain tissue of triple transgenic Alzheimer’s disease mouse models (3 × Tg-AD)." (PMID 41178992, 2025). "Decreased levels of mtDNA and TFAM with impaired mitochondria have been reported in many neurodegenerative diseases, including PD, Alzheimer’s disease as well as in aging." (PMID 35955761, 2022). "Interestingly, the mitochondrial transcription factor A (TFAM) is a key regulator of the mitochondrial genome and copy number has been linked to neurodegenerative diseases like Alzheimer’s disease and Parkinson’s disease." (PMID 39487142, 2024). "Additionally, one study showed that 12-week treadmill training also increased the protein levels of biogenesis regulators (SIRT1, PGC-1α, and TFAM) along with the reduction of beta-amyloid accumulation in the brain of Alzheimer’s disease rats model." (PMID 34440215, 2021). "TFAM binds to mtDNA and forms a nuclear-like structure, thereby protecting mtDNA from the adverse effects of Aβ toxicity and oxidative stress, inhibiting the vicious cycle of neuronal mitochondrial dysfunction, and thus improving the pathophysiology of Alzheimer’s disease." (PMID 40463912, 2025).
glioma (14 papers, 2015 to 2026). A benign or malignant brain and spinal cord tumor that arises from glial cells (astrocytes, oligodendrocytes, ependymal cells). "The current findings identify TFAM as a context-dependent regulator of glioma cell phenotype, with its loss driving proliferative, ROS-prone states in GPM GBM cells but eliciting adaptive stress-resilient programs in MTC-type cells." (PMID 41226485, 2025). "Although these studies elucidate an association between gliomas and TFAM, the mechanism underlying TFAM’s contribution to glioma pathogenesis is poorly understood." (PMID 37332990, 2023). "A specific and direct binding of KLF16 to the BTE region in TFAM promoter has been demonstrated by chromatin immunoprecipitation assay in glioma cells." (PMID 41424862, 2026). "The observation with the mutants further implying a positive regulatory relationship between FoxM1 and TFAM in glioma cells." (PMID 41323781, 2025). "To observe the relationship between FoxM1 and TFAM, we first analyzed the expression levels of FoxM1 and TFAM in glioma specimens from TCGA." (PMID 41323781, 2025). "In conclusion, our experimental evidence underscores the critical role of FoxM1 N-terminal domain R15 in its transcriptional activity, nuclear localization, TFAM expression and regulation of mitochondrial dynamics in glioma cells." (PMID 41323781, 2025). "Future work should explore pharmacological modulation of TFAM and its effectors as a precision medicine strategy in high-grade gliomas." (PMID 41226485, 2025). "Taken together, these findings confirm that FoxM1 is a positive regulator of TFAM expression and R15 site is critical for FoxM1 activity in regulating TFAM expression in glioma cells." (PMID 41323781, 2025). "Elevated TFAM expression correlated with improved patient prognosis, suggesting a protective role in glioma progression." (PMID 41226485, 2025). "At the protein level, TFAM immunostaining was assessed in 79 astrocytoma samples, comparing low-grade gliomas (AG2 and AG3) and GBMs." (PMID 41226485, 2025). "Like other TFAM studies, this study showed that TFAM expression was significantly increased in glioma tissues and positively correlated to the malignancy grade." (PMID 37332990, 2023). "Similar to the functions of TEFM in HCC, another mitochondrial transcription regulator TFAM also has been reported to induce G1 cell cycle transition, but inhibit cell apoptosis in glioma and non-small cell lung cancers." (PMID 33771980, 2021). "In line with us, a previous study in glioma cells also has shown that increased TFAM promoted tumor cell migration." (PMID 33771980, 2021). "Nevertheless, the protein levels of TFAM positively correlated with the malignancy of glioma, higher RNA levels of TFAM correlated with a better prognosis among patients with grade IV glioma (glioblastoma, GBM)." (PMID 29747444, 2018). "TFAM expression levels are elevated in glioma, and positively correlated to the malignancy of glioma." (PMID 26820294, 2016). "For example, EPA supplementation activated PGC-1α and the downstream transcription factor TFAM in glioma cells." (PMID 26010060, 2015). "TFAM is upregulated in glioma 14 and is correlated to malignancy grade 15." (PMID 41323781, 2025). "Furthermore, analyses using TCGA database showed that PGC1α and TFAM expression in Grade 4 gliomas patients were lower than those in Grade 3 patients, and that higher PGC1α and TFAM expression were correlated with better prognosis." (PMID 38702818, 2024). "TFAM can act alone as an epigenetic mechanism in glioma pathogenesis." (PMID 37332990, 2023). "Moreover, FoxM1 overexpression counteracted the suppression of TFAM by siRNA in glioma cells." (PMID 41323781, 2025). "Nonetheless, TFAM may be a strong candidate target for glioma therapeutic interventions." (PMID 37332990, 2023).
glioma (continued). "We found that VEGFR2 expression was higher in grade III and IV glioma patients than that in grade II patients, and that VEGFR2 blockade inhibits glioblastoma cell growth via AKT-PGC1α-TFAM-mitochondria biogenesis signaling cascade." (PMID 38702818, 2024). "In patients with glioma, KLF16 serves as a key regulator of glioma cell proliferation by binding to the TFAM promoter, leading to the reduction of TFAM expression." (PMID 32824374, 2020). "In glioma, the TFAM RNA and protein levels are upregulated, compared to non-neoplastic brain tissue." (PMID 29747444, 2018). "Others also demonstrated in C6 glioma cells that n-3 PUFAs are ligands for receptors that activate PGC-1α, leading to increased expression of PGC-1α, transcription factor-A mitochondrial (TFAM), cytochrome c oxidase, and increased the mitochondrial membrane potential." (PMID 26010060, 2015).
melanoma (14 papers, 2017 to 2025). A malignant, usually aggressive tumor composed of atypical, neoplastic melanocytes. "In this study, we performed a correlation analysis of mtDNA content, mutational load, and TFAM expression with the energetic metabolism of melanoma cell lines." (PMID 30242167, 2018). "Integrated genomics analysis confirmed that TFAM is a critical driver in drug resistance in melanoma." (PMID 35308143, 2022). "Then, qRT-PCR analysis confirmed that overexpression of miR-181a/b markedly inhibited TFAM expression on mRNA level in both sensitive and resistant A375 melanoma cells." (PMID 33670365, 2021). "It has been shown that TFAM acts as an oncogene in melanoma regulating metabolic and mitochondrial genes." (PMID 33670365, 2021). "In fact, a recent paper demonstrated that TFAM acts as an oncogene by transcriptionally regulating metabolic and mitochondrial gene signatures in melanoma." (PMID 33670365, 2021). "An extensive list of transcription factors has been directly linked with metabolic plasticity during melanoma metastasis and adaptive resistance to MAPKi (HIF1α, MYC, MITF, PGC1α, PPARα, TFAM)." (PMID 34830962, 2021). "Our results strongly support a central role for the miR-181a/b-TFAM axis in modulating key components of tumor growth with target therapy resistance both in vitro and in vivo melanoma models." (PMID 33670365, 2021). "Introduction of miR-181 mimics markedly decreases the expression of TFAM in A375 melanoma cells resistant to BRAF inhibitors." (PMID 33670365, 2021). "In this study, we undertook several novel approaches to investigate the relationship between mtDNA alterations and TFAM expression to energetic metabolism in melanoma cell lines." (PMID 30242167, 2018). "Due to high heterogeneity among cancer types, we believe that only an in vivo analysis using a melanoma model can confirm the tumorigenic role of TFAM in melanomagenesis." (PMID 30242167, 2018). "In conclusion, our study employs multiple bioinformatic and in vitro approaches to evaluate the role of TFAM in melanoma cell lines and metastatic melanoma tumors." (PMID 30242167, 2018). "Here, we use melanoma cell lines and metastatic melanoma tumors to evaluate the effect of mtDNA alterations and the expression of the mtDNA packaging factor, TFAM, on energetic metabolism and pro-tumorigenic nuclear gene expression changes." (PMID 30242167, 2018). "Similar to our analysis in melanoma cell lines, we divided the melanoma tumors by TFAM expression, applying a cut-off of 25 and 75 percentiles to select samples with low TFAM expression (TFAM down, n = 32) and high TFAM expression (TFAM up, n = 32)." (PMID 30242167, 2018). "Our findings contribute to the understanding of how TFAM affects melanoma cell metabolism, and they provide new insight into the mechanisms by which TFAM and mtDNA copy number influence melanoma tumorigenesis." (PMID 30242167, 2018). "The down regulation of glycolytic enzymes corroborates our previous findings that TFAM down melanoma cell lines indeed consumed less glucose." (PMID 30242167, 2018). "As positive correlation between mtDNAcn and TFAM is well described in the literature, we focused solely on the impact of TFAM on gene expression of melanoma cell lines." (PMID 30242167, 2018). "Our findings therefore expand the understanding of TFAM in cancer, and provide new insight into its diverse roles in shaping melanoma metabolism, growth, and invasion." (PMID 30242167, 2018). "We then expanded our data using melanoma cell lines and metastatic melanoma samples, and observed that TFAM mediates the expression of metabolic genes, demonstrating a role for this mitochondrial transcription factor in metabolic reprogramming." (PMID 30242167, 2018). "Our expanded panel showed that melanoma cell lines were very heterogeneous in terms of TFAM expression." (PMID 30242167, 2018).